MTOR (mechanistic target of rapamycin kinase)
Diseases named in the same sentence as MTOR in open-access papers (continued):
Sharing a sentence is not in itself a finding about the gene and the disease.
glioblastoma (continued). "In conclusion, we demonstrate for the first time that XHP may regulate glioblastoma U-87 MG cell apoptosis via ROS-mediated Akt/mTOR/FOXO1 pathway." (PMID 30046342, 2018). "Therefore, we treated U87-MG glioblastoma cells with various concentrations of two mTOR inhibitors, temsirolimus and rapamycin, in combination with COTI-2." (PMID 29364966, 2018). "Moreover, inhibition of DSB repair system with PI3K/mTOR inhibitor NVP-BEZ235 attenuated the repair of ionizing radiation-induced DNA damage in glioblastoma model." (PMID 29435166, 2018). "Consistent with this hypothesis, blockade of mTOR signaling by inhibitors of mTOR or EGFR promote nuclear PML expression in glioblastoma cells." (PMID 30374421, 2018). "An increase in the hyperpolarized lactate-to-pyruvate ratio has been shown in murine models of glioblastoma, and a decrease in this ratio has been shown to follow treatment with inhibitors of the phosphoinositide 3-kinase/mammalian target of rapamycin (PI3K/mTOR) and temozolomide." (PMID 29459844, 2018). "We investigated whether a combination of the dual pan-Class I PI3K/mTOR inhibitor PI-103 with TMZ in paediatric glioblastoma cell lines would show changes in their metabolic profiles that could be detected with NMR." (PMID 28704425, 2017). "Downregulation of AKAP1 impaired mTOR pathway and inhibited glioblastoma growth." (PMID 28569781, 2017). "In other words, inhibiting mTOR in glioblastoma may suppress an overactive neural stem cell proliferation readdressing this exuberant cell population towards the original phenotypes." (PMID 29259984, 2017). "It has been reported that 2-HG could equally activate and inhibit mTOR in different cells (genetically manipulated glioblastoma, C. elegans etc.)." (PMID 28578659, 2017). "Taken together, our data suggest that NMR metabolites could be used as biomarkers to detect an early response to combination therapy with PI3K/mTOR inhibitors and radiotherapy in adult and pediatric glioblastoma patients." (PMID 28624789, 2017). "Importantly, mTOR inhibition related to feedback activation of PI3K/Akt signaling and regulation of other crucial cellular signals in human glioblastoma to escape from the effect of mTOR inhibitor rapamycin." (PMID 27329594, 2016). "It was reported that down-regulated uPA expression could inhibit AKT/mTOR signal pathway in glioblastoma cells, and AKT-mTOR signal pathway could modulate MMP-2 expression important for cleavage of the Laminin 5γ2 which was essential in the VM formation." (PMID 26992227, 2016). "Glioblastoma is a fatal and incurable cancer with the hyper-activated mTOR pathway." (PMID 27325206, 2016). "CD133 expression is enhanced under hypoxic conditions via HIF-1α/mTOR signaling in glioblastoma." (PMID 25301737, 2014). "Metformin as an mTOR inhibitor may provide an important contribution to the treatment of glioblastoma multiforme." (PMID 24940426, 2014). "This suggests that this novel method could be used to monitor modulation of the PI3K/mTOR pathway in pediatric glioblastoma." (PMID 25084455, 2014). "As PTEN expression is reduced by mutation or loss of heterozygocity in 5-40% and 60-80%, respectively, and PI3K/Akt/mTOR signaling is elevated in ~88% of all glioblastoma, the addition of pharmacological inhibitors to current treatment schedules should lead to clear therapeutic benefits." (PMID 26056598, 2014). "Several factors may contribute to this minimal antitumor response to combination therapy of EGFR and mTOR inhibitors in glioblastomas, including mainly therapy resistance or use of inadequate drug doses." (PMID 22530122, 2012). "In U87-MG cells baseline levels of some VEGF isoforms under normoxia, mainly VEGF189 were high due to hypoxia-independent mechanisms as reactive oxygen species, NO, phosphatidylinositol-3-kinase and MAP kinase activation through the action of mTOR, or loss of IDH1 gene function in glioblastoma." (PMID 21949677, 2011).
glioblastoma (continued). "This was observed in a Phase I clinical trial investigating the impact of the mTOR inhibitor, Rapamycin, in PTEN-deficient glioblastoma; the drug proved effective in suppressing disease progression in some patients but appeared to accelerated disease in others." (PMID 21479172, 2011). "Although the mTOR pathway has been reported to be important for the viability and maintenance of breast and glioblastoma CSCs, inhibition of mTOR with rapamycin in H-Ras-transformed mouse liver cancer cells significantly increased the proportion of CD133+ cells and retained the stemness properties." (PMID 22145042, 2011). "Akt activates mammalian target of rapamycin (mTOR), which is deregulated in glioblastoma." (PMID 20576128, 2010). "In preclinical studies, PTEN-deficient tumors showed enhanced sensitivity to mTOR inhibitors, and thus the frequency of inactivating PTEN mutations in glioblastoma suggests that mTOR inhibitors may be used to successfully treat glioblastoma." (PMID 20652056, 2010). "The mTOR is a validated target in many human cancers, and rapamycin analogs (rapalogs) have shown promising results in various tumor types, including non-Hodgkin's lymphoma, sarcoma, glioblastoma and endometrial cancer." (PMID 20630061, 2010). "EGFR, encoding a transmembrane receptor tyrosine kinase acting in the PI3K/AKT/mTOR, MAPK, and other pathways, is among the genes most frequently activated by gene amplification, genetic rearrangements, and single nucleotide variants in IDH-wildtype glioblastomas." (PMID 41546701, 2026). "Additionally, in glioma (GBM), the PLGA-CMB microbubble complex combined with ultrasound technology overcame the blood-brain barrier, enhanced drug delivery via the cavitation effect, inhibited the PI3K/Akt/mTOR pathway, and induced apoptosis in glioblastoma stem cells (GSCs)." (PMID 41311720, 2025). "In cancers with mTOR gain-of-function mutations, such as glioblastoma or renal cell carcinoma, CRISPR-Cas9 can be used to selectively knock out the mutated allele, thereby reducing excessive mTOR signaling, which could help control tumor growth driven by mTOR overactivation." (PMID 40358185, 2025). "Agents such as tyrosine kinase inhibitors and mTOR inhibitors have been investigated; however, their efficacy has been limited in clinical settings, often due to the complex and heterogeneous nature of glioblastoma, as well as the blood–brain barrier, which restricts drug delivery." (PMID 39796773, 2025). "Loss of phosphatase and tensin homolog deleted on chromosome 10 (PTEN) in primary human glioblastoma (GBM) stabilized ARL4C due to the AKT/mTOR pathway-mediated inhibition of ARL4C ubiquitination." (PMID 39767779, 2024). "Definitely, the PI3K/AKT/mTOR pathway will become a possible pharmaceutical target in the fight against primary brain tumors; countering the abnormal function of one of these factors could lead to a valid therapeutic approach in the glioblastoma contest." (PMID 37759505, 2023). "However, the complexity of the mTOR signaling, off-target effects, cytotoxicity, suboptimal pharmacokinetics, and drug resistance of the mTOR inhibitors pose ongoing challenges in effectively targeting glioblastoma." (PMID 37834408, 2023). "Moreover, glioblastoma patients with EGFR mutations or amplifications may have increased mTOR pathway activation, making mTOR inhibitors more effective in blocking downstream signaling." (PMID 37834408, 2023). "Also, ARG may suppress glioblastoma development by activating autophagy through the AKT/mTOR pathway." (PMID 36852795, 2023).
glioblastoma (continued). "In addition, further experiments using glioblastoma stem cell organoids as recently shown for the combination of a Mammalian Target of Rapamycin (mTOR) inhibitor and TTFields might validate our findings." (PMID 36902447, 2023). "It is well known that glioblastoma multiforme (GBM), a lethal brain tumor, features mTOR overactivation, which is concomitant with autophagy suppression." (PMID 35326535, 2022). "Thus, mTOR has been considered as a potential therapeutic target for glioblastoma treatment." (PMID 35239512, 2022). "Studies showed that activation of the mTOR pathway has been identified in benign and malignant NF1 tumors, suggesting that activation of autophagy by inhibiting mTOR pathway could be a potential therapeutic strategy for optic neuropathy in patients with glioblastoma." (PMID 34980273, 2022). "Moreover, BBR has been suggested to induce autophagy in glioblastoma by targeting the AMP-activated protein kinase (AMPK)/mechanistic target of rapamycin (mTOR)/ULK1 pathway and in liver cancer cells by stimulating the release of beclin-1 from the Bcl-2/beclin-1 complex." (PMID 35572960, 2022). "Contrary to this, other studies showed that dual inhibitor (NVP-BEZ23) of the P13K/mTOR signaling pathway can enhance autophagy through affecting the ATG5 and Beclin1 autophagy-linked proteins and DNA damage repair proteins functions, and can stimulate the radiation sensitive glioblastoma cells." (PMID 33525678, 2021). "Among the top significant associations, Asian cell lines showed higher sensitivity to PI3K/mTOR inhibitors, especially in glioblastoma (GBM)." (PMID 34576298, 2021). "However, DCA reduced the abundance of PDK1 protein in glioblastoma cells in one hour, implicating a role for the post-transcriptional mechanisms, such as regulation of the translation by the mammalian target of rapamycin (mTOR) or proteolysis." (PMID 34445316, 2021). "The molecular target of rapamycin (mTOR) has been reported to be upregulated in glioblastoma, where it controls cell growth rate, stem cell proliferation, and GBM recurrence." (PMID 34571747, 2021). "Therefore, there are convincing experimental evidences indicating that fucoxanthin exerts antiglioma activity, promotes apoptosis via PI3K/Akt/mTOR pathway inhibition and suppresses tumor invasion and migration due to the restriction of the p38/MMPs signaling pathway in human glioblastoma cells." (PMID 34440090, 2021). "While the TSC2 mutation in conjunction with high mTOR expression may suggest treatment with everolimus, clinical evidence of activity in glioblastoma has not been supportive." (PMID 34943910, 2021). "However, it is found that overactivation of the PI3K/AKT/mTOR pathway reduces in the survival of glioblastoma patients and increases in the aggression of the tumor as it overstimulates processes responsible for cell proliferation, survival and migration in glioblastoma." (PMID 32290213, 2020). "With regard to glioblastoma-associated signaling, metformin may interfere with AMPK activity, which in turn modulates (suppression) mTOR signaling relevant for tumor growth and invasion, as regulated during tumor development via the DNS damage response (REDD1) pathways and oxidative stress." (PMID 33316976, 2020). "Riluzole also demonstrated synergistic anti-glioblastoma (GBM) affects with mTOR inhibitors in vitro and in GBM xenografts in mice." (PMID 31948038, 2020). "Since rapamycin has been reported to induce apoptosis in glioblastoma, we wanted to determine the rapamycin-induced effects on mitochondria, in addition to decreasing mTOR signaling, as a means of searching for new mitochondria-targeted therapies to treat GBM." (PMID 33162811, 2020). "Therefore, researchers have identified PI3K, AKT, and mTOR as molecular targets for glioblastomas." (PMID 32290213, 2020).
glioblastoma (continued). "SCD1 expression is reported to stimulate following activation of PI3K-Akt-mTOR pathway in cancer cells and therefore has been investigated as a therapeutic target in a variety of human cancers including colon, endometrial, glioblastoma, lung, and renal cell carcinoma." (PMID 32155177, 2020). "In contrast, there is increasing evidence of mTOR upregulation in both experimental and human Glioblastoma Multiforme (GBM)." (PMID 29259984, 2017). "Our ex vivo data are in line with our in vitro results, and clearly show that NMR may be used successfully to detect a decrease in several metabolites, in particular lactate and tCho following inhibition of the PI3K/mTOR pathway and radiation treatment of glioblastoma." (PMID 28624789, 2017). "Thus, the combined therapy of EMAP II with agents that can inhibit P13K/Akt/mTOR signal pathway may be a new novel therapeutic strategy for the treatment of human glioblastoma." (PMID 26648842, 2015). "The PI3K/AKT/mTOR pathway is commonly over activated in glioblastoma (GBM), and Rictor was shown to be an important regulator downstream of this pathway." (PMID 23555046, 2013). "Besides direct VEGF or VEGFR2 inhibition for glioblastoma, clinical studies are being conducted or planned with agents targeting further downstream or alternative pathways frequently altered in brain tumors, including the mTOR/Akt and EGFR pathways." (PMID 21771332, 2011). "The efficacy of mTOR inhibitors in glioblastoma cell lines has prompted their clinical trials for GBM." (PMID 20576128, 2010). "Some of the signaling pathways involved in glioblastoma progression include ERK, NF-κB, Wnt, and PI3K/AKT/mTOR." (PMID 42274584, 2026). "In glioblastoma models, phloridzin improves the cytotoxic effects of temozolomide (TMZ) by suppressing PI3K/AKT/mTOR signaling, leading to increased apoptosis." (PMID 40761486, 2025). "NRG1 is a prognostic biomarker in glioblastoma, it promotes malignancy by inhibiting autophagy via AKT/mTOR pathway." (PMID 40959099, 2025). "Plinabulin effectively inhibited the proliferation of glioblastoma cells and induced autophagy by targeting the PI3K/AKT/mTOR pathway." (PMID 39877641, 2025). "In Glioblastoma (GBM), LINC00470 from GBM derived-exosomes activates PI3K/AKT/mTOR signaling to suppress autophagy and promote glioma cell growth." (PMID 40651979, 2025). "Mechanistically, STLs have been shown to induce apoptosis in GSCs by modulating signaling pathways such as PI3K/AKT/mTOR and MAPK/ERK, which are frequently deregulated in glioblastoma." (PMID 39857717, 2025). "CD47 has been confirmed to promote the invasion of glioblastoma and endometrial carcinoma cells via the PI3K/AKT/mTOR-mediated glycolysis pathway." (PMID 38317230, 2024). "Particularly in HGG IDH—wildtype glioblastoma, alterations in the PI3K-Akt-mTOR pathway were discovered in 80% of samples." (PMID 39684714, 2024). "EGFR amplification has been reported in up to 45% of patients with glioblastoma, and numerous studies have demonstrated the important role of the EGFR/PI3K/AKT/mTOR signaling pathway in glioblastoma progression." (PMID 38315329, 2024). "In TMZ-resistant glioblastoma multiforme (GBM), autophagy sensitizes TMZ treatment by inhibiting the AKT/AMPK/mTOR pathway." (PMID 38671354, 2024). "Glioblastoma involves a complex interplay of molecular signaling pathways, among which the PI3K/Akt/mTOR pathway stands out." (PMID 38893207, 2024). "In quiescent glioblastoma (GBM) cells, the platelet-derived growth factor (PDGF)-induced localization of mTOR in the nucleus was reduced by pretreatment with rapamycin." (PMID 38474373, 2024). "In glioblastoma, EPZ015666 overcame therapeutic resistance to the mTOR inhibitor PP242 via synergistic tumour inhibitory effects in vitro and xenograft mouse models in combination with the mTOR inhibitor PP242." (PMID 39703687, 2024).
glioblastoma (continued). "In addition, CD47-targeting immune checkpoint inhibition can induce GBM cell death via Akt/mTOR inactivation and elevated autophagic flux in glioblastoma cell lines." (PMID 38890642, 2024). "In conclusion, metformin shows antineoplastic mechanisms against glioblastoma cells by increasing apoptosis and autophagy and inhibits cancer cell growth by blocking the LKB1/AMPK/mTOR/S6K1 pathway." (PMID 38891882, 2024). "Moreover, there is benzofuran, 6-ethenyl-4,5,6,7-tetrahydro-3,6-dimethyl-5-isopropenyl-, trans- or curzerene, which is the main compound in CAEO that could induce cell apoptosis in glioblastoma cell lines by inhibiting the mTOR pathway and downregulating GSTA4." (PMID 38166788, 2024). "Apitolisib (GDC-0980), a novel dual PI3K/mTOR inhibitor of mTORC1/2 and PI3K class I tested in solid tumors, including those of the brain, inhibits growth and induces apoptosis in human glioblastoma cells." (PMID 39410026, 2024). "Overall, E2F7 is responsible, in part, for the proliferative advantages in glioblastoma mediated by EZH2 inhibition of PTEN and leading to activation of the PI3K/AKT/mTOR pathway." (PMID 38183103, 2024). "It has been shown that endothelial monocyte-activating polypeptide II induces mitophagy and cytotoxicity in human glioblastoma cells and glioblastoma stem cells through inhibiting the PI3K/Akt/mTOR signal pathway." (PMID 38393028, 2024). "A phase II trial for glioblastoma (GBM) patients with MGMT unmethylation reported that the mTOR inhibitor temsirolimus could prolong overall survival in patients with mTORSer2448 phosphorylation." (PMID 37545464, 2024). "While the precise role of the RAS/RAF/MAPK pathway in glioblastomas is still the subject of research, the PI3K/AKT/mTOR pathway in glioblastomas has been studied in detail." (PMID 37907716, 2023). "Clinically, Rios and colleagues described a case of a glioblastoma patient treated with AMD3100 (plerixafor) and a combination of a mammalian target of rapamycin (mTOR), a Sirtuin-1 (Sirt1), and an EGFRvIII inhibitor after conventional chemo-radiotherapy." (PMID 36980182, 2023). "In glioblastoma stem-like cells, mepazine, another MALT1 inhibitor, and MALT1 siRNA were reported to blunt mTOR activation, as assessed through the phosphorylation of Akt, p70 S6K, and S6 ribosomal protein." (PMID 38097554, 2023). "Additional studies on glioblastoma cell line U251 showed that when cells were treated with curcumin, phosphorylation levels of AKT and mTOR were significantly decreased." (PMID 37998723, 2023). "Many mTOR and PI3K inhibitors were designed and developed from PI103, and they all significantly affected glioblastoma." (PMID 37834408, 2023). "A new PI3K/mTOR inhibitor (GDC-0084) dramatically inhibits the proliferation of glioblastoma cells in in vitro and effectively inhibits the growth of U87 MG glioblastoma in tumor-bearing mice via lowering AKT phosphorylation." (PMID 37834408, 2023). "Metformin and resveratrol antidiabetic drugs show antineoplastic mechanisms against glioblastoma cells by increasing apoptosis and autophagy and decreasing proliferation by altering the PI3K/Akt, mTOR, AMPK, MAPK, and mitochondrial pathways." (PMID 37444478, 2023). "Nevertheless, it is intriguing that molecular determinants (TGF-β, mTOR and STAT3) either in the glioblastoma cellular states and/or in the tumour microenvironment converge as regulators of NBCe1 activity." (PMID 36012235, 2022). "NF-κB is constitutively overexpressed in glioblastoma and its aberrant activation is connected to EGFR deregulation (which promotes tumor cell proliferation and survival) and the PI3K/Akt/mTOR signaling pathway." (PMID 35328780, 2022).